HNF1A (HNF1 homeobox A)
Diseases named in the same sentence as HNF1A in open-access papers (continued):
Sharing a sentence is not in itself a finding about the gene and the disease.
MODY (continued). "The biggest subtype, MODY, can be caused by a dysfunction in one of 11 genes, of which the gene encoding hepatocyte nuclear factor-1 alpha (HNF1A) serves as the largest contributor in Norway." (PMID 37798422, 2023). "A total of 14 missense HNF1A variants identified in 20 clinical MODY patients were included in this study." (PMID 37396188, 2023). "Summary of re-interpretation of HNF1A gene variants and their clinical actionability, identified in Indian MODY patients based on molecular characterization." (PMID 37396188, 2023). "Hnf-1α is very important for beta cell formation and adult beta cell function, and HNF-1α mutations are the most common cause of MODY subtype 3." (PMID 36232358, 2022). "Common genetic variants influencing the age at onset of HNF1A-MODY were sought through a genome-wide study." (PMID 36104811, 2022). "MODY3 (maturity-onset diabetes of the young, type 3) is the most common form of MODY, which is caused by heterozygous variants in hepatocyte nuclear factor 1 alpha (HNF1a)." (PMID 36361808, 2022). "The majority of patients with a genetic a diagnosis of MODY (>80%) will have mutations in the HNF1A, HNF4A or GCK genes, and a genetic diagnosis of these subtypes has important implications for precision medicine‐based clinical care." (PMID 35445424, 2022). "HNF1A-MODY accounts for approximately 30%–50% of the MODY cases, with nearly 414 mutations detected in 1247 families diagnosed." (PMID 36361703, 2022). "People with MODY and heterozygous HNF1A or HNF4A mutations are also highly sensitive to sulfonylureas." (PMID 35618782, 2022). "More than 400 causative variants segregating with MODY have been identified across the HNF1A gene, having diverse effects on protein properties and cellular phenotypes." (PMID 36104811, 2022). "Since an HNF1α allele is normal in MODY patients, it can be deduced that the expression level of HNF1α is important in this group." (PMID 35299962, 2022). "HNF1A MODY-causing mutations are the most prevalent in European, North American, and Asian populations; accounting for 20–50% of all MODY cases." (PMID 36613572, 2022). "Of the 89 eDia3 patients, 10 (11.2%) carried likely pathogenic variants in genes (KLF11, GCK, ABCC8, PAX4, BLK and HNF1A) of MODY." (PMID 35921062, 2022). "We assessed the age-related penetrance of pathogenic HNF1A variants in MODY probands (n = 661), their family members (n = 622), a health-system-based cohort (Geisinger cohort n = 132,194) and a population-based cohort (UK Biobank n = 198,748)." (PMID 36257325, 2022). "MODY is primarily caused by a defect in pancreatic β-cells’ glucose-stimulated insulin production, highlighting the critical functions of HNF1A and HNF4A in -cells." (PMID 36037214, 2022). "For example, the level of insulin sensitivity in MODY caused by variants in HNF1A (HNF1A-MODY) depends on the comparator group and their genetic background, perhaps irrespective of HNF1A altogether." (PMID 34951657, 2022). "Recently, however, a biallelic mutation of this gene was found to be related to MODY and to cause primary hepatocellular adenoma co-occurring with HNF1A-MODY." (PMID 34299172, 2021). "Three-quarters (72/95) of the positively tested family members had a mutation in the GCK gene (presented in Part II of this article), around 20% (18/95) in the HNF1A gene and 5% (5/95) in other MODY-causing genes." (PMID 34440499, 2021). "The mutations in HNF1A, linked to MODY, are heterozygous, scattered throughout the protein coding region, promoter and 5′-UTR and consist of missense, nonsense and frameshift mutations." (PMID 34299172, 2021). "The frequency of mutations in the major MODY genes (HNF4A, GCK, and HNF1A) has been shown to be extremely low among Korean patients with MODY." (PMID 33663443, 2021). "We identified a total of 22 missense variants (3 novel variants) in 27 patients (60.0%) in the GCK, HNF4α, and HNF1α genes in this study involving a small set of 45 Japanese pediatric MODY patients." (PMID 34746319, 2021).
MODY (continued). "More than 70% of disease-causing mutations were found in the GCK gene, about 20% in the HNF1A gene and less than 10% in other MODY-causing genes." (PMID 34440499, 2021). "HNF1A-MODY has age-dependent high penetrance; almost 63% of the patients with HNF1A mutations develop symptoms by the age of 25, 93.6% by the age of 50 years, and 98.7% by the age of 75 years." (PMID 34440499, 2021). "Depending on the mutations found within HNF1A, their effects can be benign, cause MODY, or act as a risk factor for T2DM." (PMID 34299172, 2021). "In Japan, variants in the HNF1α gene are the most commonly identified MODY genes, which is consistent with studies on the European population." (PMID 34746319, 2021). "More than 70% (65/89) of the mutations were found in the GCK gene (described in Part II of this article), around 20% of the mutations (17/89) were found in the HNF1A gene and the remaining roughly 10% (7/89) in other MODY-causing genes." (PMID 34440499, 2021). "GCK, HNF4A, and HNF1A were the most frequently reported pathogenic genes causing MODY in Europeans, which accounts for approximately 94% of cases." (PMID 32411229, 2020). "Mutations in the glucokinase (GCK) gene, along with hepatocyte nuclear factor 1A (HNF1A) gene, are the most frequent causes of MODY." (PMID 31739614, 2019). "In another study in patients with different MODY types, hsCRP level was lowest in HNF1A mutations carriers." (PMID 30778899, 2019). "In MODY, genetic analysis was performed in 26 (59%) patients and HNF1A and GCK gene mutations were detected in 3 (11.5%) and 14 (53.8%) patients, respectively." (PMID 29175806, 2018). "A total of 4.1% of individuals had likely pathogenic or pathogenic variants in the commonest MODY genes (HNF1A, HNF4A, HNF1B, GCK or INS)." (PMID 30377832, 2018). "The majority of MODY cases are accounted for by mutations in one of four genes: the transcription factors, hepatocyte nuclear factor 1-alpha (HNF1A), 4-alpha (HNF4A), 1-beta (HNF1B) and the enzyme, glucokinase (GCK)." (PMID 30377832, 2018). "In MODY, genetic analysis was available in 26 (59%) patients and HNF1A and GCK gene mutations were detected in 3 (11.5%) and 14 (53.8%) patients, respectively." (PMID 29175806, 2018). "Even though there were two cases reported three people with HNF1A-MODY developed to severe DKA, the present diagnostic recommendations suggest that the people with DKA would be excluded from MODY." (PMID 28105082, 2017). "A missense mutation of HNF1A gene was first found in Chinese ketosis-prone MODY family with manifestations heterogenicity among the persons." (PMID 28105082, 2017). "MODY 3 is caused by hepatocyte nuclear factor-1A (HNF1A) gene mutation (also named as HNF1A-MODY), which accounts for 30–50% of MODY." (PMID 28105082, 2017). "Most MODY cases result from mutations within the hepatocyte nuclear factor 1 alpha (HNF1A) and glucokinase (GCK) genes." (PMID 28593615, 2017). "Common variants in MODY genes, especially in HNF1A and GCK, have been correlated with GDM and related traits." (PMID 28133617, 2017). "It was found that individuals with MODY carrying mutations in the HNF1A or HNF4A genes are sensitive to low-dose sulfonylureas, though the mechanism is incompletely understood." (PMID 28447115, 2017). "MODY caused by mutations in the HNF1A gene is a very good example of how dissecting the aetiology of diabetes leads to personalized treatment." (PMID 26802434, 2016). "HNF1A is also a common cause of MODY in many populations, with more than 193 mutations being described." (PMID 26981542, 2016). "Mutations in HNF1A were shown to lead to maturity onset diabetes of the young (MODY), which is known as MODY3." (PMID 26252223, 2015). "Although impaired function of only one protein is linked to the pathophysiology of HNF1A MODY, the molecular mechanisms responsible for the clinical outcome of the patients are not fully understood, mainly due to the poor accessibility of affected tissues." (PMID 25716801, 2015).
MODY (continued). "In contrast, MODY3 caused by HNF1A mutations, the most common type of MODY that accounts for ∼63% of all MODY cases, tends to have obvious glycosuria because of impaired glucose-stimulated insulin secretion, as well as decreased renal threshold for glucose." (PMID 25136813, 2014). "Mutations in the HNF1A gene are the most common cause of MODY in the UK, accounting for approximately 50% of their cases." (PMID 24069322, 2013). "HNF4A-MODY caused by mutations in the HNF4A gene is relatively less common than HNF1A mutations and accounts for approximately 5% of MODY cases worldwide." (PMID 23803251, 2013). "The most common subtypes of MODY in all populations studied are the result of mutations in the genes encoding the transcription factor Hepatocyte nuclear factor 1 alpha (HNF1A) and the key glycolytic enzyme glucokinase (GCK)." (PMID 22859960, 2012). "The answer is yes, as identifying MODY can guide management and more specifically, further subtyping of MODY based on genotypes can lead to individualized treatment such as the use of sulfonylureas in HNF1A and HNF4A mutations." (PMID 22936918, 2012). "HNF1A-MODY is associated with a severe and progressive clinical course with up to 50% of patients requiring insulin." (PMID 22808921, 2012). "The aim of this study was to perform metabolic profiling in urine from patients with MODY due to mutations in the genes encoding glucokinase (GCK) or hepatocyte nuclear factor 1 alpha (HNF1A), type 2 diabetes (T2D) and normoglycaemic control subjects." (PMID 22859960, 2012). "Although the possibility that MODY mutations have a causal role in this group is remote, the exclusion of the most common MODY mutations by sequencing the whole HNF1A and GCK genes is necessary given the peculiar inheritance and onset patterns." (PMID 19490620, 2009). "Whilst initial in vitro characterisation of the common P291fsinsC mutation in HNF1A suggested a dominant-negative mechanism, it has been subsequently shown that MODY is most likely a disease of haploinsufficiency." (PMID 19787084, 2008). "A clinical diagnosis of MODY was considered, likely HNF1A or HNF4A mutation." (PMID 40777711, 2025). "The most commonly diagnosed variant—MODY3—caused by a mutation in the hepatocyte nuclear factor 1-alpha (HNF1A) gene, accounts for roughly 69% of MODY cases, while the other two predominant types, glucokinase (GCK) and HNF4A, contribute to approximately 20% and 3%, respectively." (PMID 40649834, 2025). "Notably, up to 80% of all cases of MODY are attributable to heterozygous variants in the HNF1A/4A and GCK genes." (PMID 41497485, 2025). "HNF1α (also known as HNF3) is the most common genetic cause of MODY in adult populations." (PMID 40149950, 2025). "The most frequent cause of MODY in patients from European populations is damage to the HNF1A gene." (PMID 39902162, 2024). "Ranging from 80% to 95% of MODY cases, the underlying cause involves the pathogenetic variants of hepatocyte nuclear factor-1 homeobox A (HNF1A), hepatocyte nuclear factor-4 homeobox A (HNF1A), hepatocyte nuclear factor-1 homeobox B (HNF1B), and glucokinase (GCK) genes." (PMID 39201476, 2024). "Variants in the HNF1A and HNF4A genes are associated with maturity-onset diabetes of the young (MODY)." (PMID 38855865, 2024). "On the other, maturity onset diabetes of the young (MODY) is a monogenic disease where pathogenic mutations in specific genes (GCK, HNF1A, HNF4A, etc.)have been identified." (PMID 34668636, 2022). "Similarly, an UK study demonstrated that the mutation pick-up rate of MODY genes (HNF1A, HNF4A, HNF1B, or GCK) in South Asian participants was 12.6%, lower than White European group (25.2%)." (PMID 35921062, 2022). "P112L and Q466X mutations of HNF1A have been associated with MODY." (PMID 35327967, 2022). "In UK, variants in HNF1A were responsible for 52% of all MODY cases, followed by 32% of GCK-MODY." (PMID 35592779, 2022). "Among these, HNF1A gene mutations are the most common cause of MODY." (PMID 35328643, 2022).
MODY (continued). "In the aggregate of the three commonest genes for MODY, approximately 1:2,100 (95%CI 1:2,700 to 1:1,640) and 1:1,500 (1:1,750 to 1:1,250) individuals harbor a pathogenic variant for HNF1A, HNF4A, or GCK in the Geisinger and UK Biobank population cohorts, respectively." (PMID 36257325, 2022). "Mutations in another HNF family member, HNF1A, are responsible for the majority of MODY cases. human embryonic stem cells (hESCs) containing HNF1A+/− and HNF1A−/− mutations when differentiated to pancreatic endocrine cells showed that balance between expression levels of different hormones was lost." (PMID 35640144, 2022). "In fact, several functionally validated HNF1A mutations have been found in MODY patients." (PMID 35327967, 2022). "ABCC8 mutations can cause MODY in patients whose clinical features are similar to those with HNF1A/4AMODY, and some patients with ABCC8 mutations were able to change from insulin to oral glibenclamide therapy, which means that patients with ABCC8presented with T2DM-like phenotypes." (PMID 35992135, 2022). "Similarly, since HNF1A mutations are commonly found in MODY patients, it is clinically important to verify the risk of liver cancer development in MODY patients." (PMID 35327967, 2022). "Similarly, MODY 3 cases resulting from variants in HNF1A are of significant clinical relevance as they provide a basis for individualized “precision” treatment and management of complications associated with glycemic control." (PMID 34373539, 2021). "The most common form of MODY is caused by mutations in hepatocyte nuclear factor 1A gene (HNF1A)." (PMID 34299172, 2021). "We identified novel potentially causative mutations p.Lys142*, Leu146Val, Ala173Glnfs*30, Val181Asp, Gly261Ala, IVS7 c.864 −1G>T, Cys371*, and Glu443Lys in GCK and Ser6Arg, IVS 2 c.526 +1 G>T, IVS3 c.713 +2 T>A, and Arg238Lys in HNF1A (both are known MODY-associated genes)." (PMID 33477506, 2021). "Maturity-onset diabetes of the young (MODY), a monogenic form of diabetes, can result from mutations in one of the genes expressed in β-cell that include GCK, HNF1A, HNF1B, HNF4A, PDX1, and B2M." (PMID 33113859, 2020). "Vascular complications are quite common in this MODY subtype and we showed that hiPSC-derived ECs with a monoallelic mutation in the HNF1A gene, as occurring in HNF1A-MODY patients, have increased vascular permeability in comparison to ECs derived from the isogenic control line." (PMID 33260307, 2020). "All five patients in the HNF1A group with mutations had PPV for MODY ≥75%." (PMID 31576961, 2020). "The three most known forms of MODY are caused by modifications to the hnf4a, gck, and hnf1a genes." (PMID 32864159, 2020). "Patients with HNF1A-maturity-onset diabetes of the young (MODY) often develop endothelial dysfunction and related microvascular complications, like retinopathy." (PMID 31739614, 2019). "UK studies reported a minimum MODY prevalence of 108 per million using data from the diagnostic sequencing laboratory (half of the cases had HNF1A-MODY) and 84 cases per million from a population-based approach (only HNF1A-MODY)." (PMID 29666556, 2018). "In fact, HNF4A acts upstream of HNF1A, mutation of which can cause a form of MODY (MODY1)." (PMID 30155490, 2018). "Both mutations cause maturity-onset diabetes of the young (MODY), and HNF1A forms heterodimers with HNF1B through their N-terminal dimerization interfaces." (PMID 28100260, 2017). "The most commonly mutated genes in MODY are HNF1A and GCK, followed by HNF4A and HNF1B." (PMID 29207974, 2017). "Patients with transcription factor-linked MODY have different associated features based on their underlying aetiology, such as glycosuria in HNF1A-MODY, fetal macrosomia and neonatal hypoglycaemia in HNF4A-MODY, and developmental disorders of the kidney and multiple other organs in HNF1B-MODY." (PMID 28314945, 2017).
MODY (continued). "In this study we have examined for the first time whether parameters derived directly from urinary glucose measurement can be used as a simple diagnostic screen for HNF1A-MODY cases." (PMID 22859960, 2012). "Furthermore the demonstration that NMD results in the destruction of several transcripts bearing PTCs, and that whole HNF1A gene deletions have been documented to cause MODY, proves it is a haploinsufficiency syndrome." (PMID 19787084, 2008). "Mutations in HNF1α protein may disrupt gene expression pathways in tissues such as the pancreas, liver, and kidneys, leading to abnormal blood glucose regulation and linking HNF1α dysfunction to both MODY and T2DM risk." (PMID 40149950, 2025). "Consequently, variants in the HNF1A gene are clinically linked to the pathogenesis of MODY." (PMID 40332430, 2025). "The finding of a novel GCK variant in our study illustrates the significant allelic heterogeneity of GCK‐MODY, and the identification of a very rare HNF1A frameshift variant shows that confirmed MODY genes may also include lineage‐specific or rare variants in Iranian families." (PMID 41497485, 2025). "It remains unclear whether the identified HNF1A c.1624-15G>A variant influences the onset of MODY." (PMID 39089324, 2024). "Furthermore, the identification of genes modifying the age of disease presentation in HNF1A variant carriers provides new insights into the pathophysiology of HNF1A-MODY, which may more broadly impact our knowledge of the regulation of glucose homeostasis." (PMID 36104811, 2022). "Interestingly, a homozygous missense HNF1A (pA251T) variant related to MODY was described recently." (PMID 34299172, 2021). "In addition, MODY can be misclassified as type 1 DM, especially in cases involving HNF1A mutations." (PMID 33663443, 2021). "Thus, we hypothesized the existence of a relationship between HNF1A mutations and phenotypes of both MODY 3 and HCA, sometimes with the two pathologies appearing in the same individuals." (PMID 31754975, 2020). "Therefore, people with mutations in HNF1A or HNF4A causing MODY can be managed with low-dose sulphonylurea therapy, and those misdiagnosed may therefore potentially stop insulin injections or have tablet regimens rationalised." (PMID 30377832, 2018). "Furthermore, MODY, especially due to HNF1A mutations can be misclassified as T1D." (PMID 29175806, 2018). "However, the mutations of HNF1A gene were detected in only 9% Chinese people with MODY, and a majority of Chinese MODY people are due to the defection of unknown genes." (PMID 28105082, 2017). "Mutations in HNF1A, encoding hepatocyte nuclear factor-1alpha, are a common cause of maturity-onset diabetes of the young (MODY) in Europeans, but not in Asians." (PMID 22350134, 2013). "Interestingly, Hnf1α is required for proper β-cell function and mutations in this gene cause MODY." (PMID 21294859, 2011). "A study from the UK Biobank provides robust statistical evidence supporting the fact that mutations in HNF1A, HNF4A, GCK, and KCNJ11 are among the most common well-established forms of MODY." (PMID 40149950, 2025). "In India, targeted next-generation sequencing of 10 MODY genes in 56 patients identified potentially pathogenic variants in HNF4A, GCK, HNF1A, PDX1, HNF1B, NEUROD1, and PAX4 in 11 individuals, suggesting a more complex etiological spectrum in this population." (PMID 41153735, 2025). "The most common mutations associated with MODY involve glucokinase (Gck) (MODY 2), hepatic nuclear factor 1-alpha (Hnf1α) (MODY 3), and hepatic nuclear factor 4-alpha (Hnf4α) (MODY 1), which together account for approximately 94% of MODY cases." (PMID 40149950, 2025). "HNF1A and GCK are among the most prevalent genes associated with MODY globally, although their frequency differs across populations." (PMID 41497485, 2025).